RN7SL176P (RNA, 7SL, cytoplasmic 176, pseudogene)
Gene: Miscellaneous RNA gene on chromosome 12 (100,158,502 to 100,158,765, reverse strand). Ensembl gene ENSG00000266610.
Homologues: Orthologues: chimpanzee Metazoa_SRP (96% identical), guinea pig Metazoa_SRP (58% identical), macaque Metazoa_SRP (56% identical), dog Metazoa_SRP (36% identical). Paralogues in human: RN7SL209P (74% identical), RN7SL196P (70% identical), RN7SL286P (70% identical), RN7SL539P (70% identical), RN7SL796P (70% identical), RN7SL545P (69% identical), RN7SL759P (69% identical), RN7SL536P (69% identical), Metazoa_SRP (69% identical), RN7SL106P (69% identical), RN7SL214P (69% identical), RN7SL238P (69% identical), and 708 more.